FRG1BP (FSHD region gene 1 family member B, pseudogene )
Synonyms: C20orf80; FRG1B; bA348I14.2
Gene: Long non-coding RNA gene on chromosome 20 (30,289,717 to 30,417,774, forward strand). Ensembl gene ENSG00000287288.
Diseases named in the same sentence as FRG1BP in open-access papers:
FRG1BP is named in the same sentence as 4 diseases in open-access papers, as found by Europe PMC text mining. Sharing a sentence is not in itself a finding about the gene and the disease. The quoted sentences say what the papers report.
ocular sarcoidosis (1 paper, 2024). A leading cause of inflammatory eye disease is sarcoidosis. "FRG1BP (previously known as C20orf80, FRG1B) has been found to be associated with body weight, body height at birth and ocular sarcoidosis phenotypes." (PMID 38052982, 2024).
prostate carcinoma (1 paper, 2022). A carcinoma that arises from epithelial cells of the prostate gland. "In SC3, FRG1BP, a gene previously associated with prostate cancer, was mutated in ~ 50% of samples in SC3 compared to less than 15% of samples in other clusters." (PMID 35439935, 2022).
tumor (1 paper, 2016). "The array data showed that 16 of the 18 selected DMRs were hypermethylated and two regions, FRG1BP and CTAGE15, were hypomethylated in primary tumors compared to tumor-adjacent normal lung tissue." (PMID 27782156, 2016).
FRG1BP also shares sentences with these, for which no sentence is quoted: cancer (1 paper).